SIM2 (SIM bHLH transcription factor 2)
Description:
Transcription factor that may be a master gene of CNS development in cooperation with Arnt. It may have pleiotropic effects in the tissues expressed during development.
Synonyms: bHLHe15; MGC119447; HMC13F06; HMC29C01; SIM
Tractability: No criterion of Open Targets' tractability assessment is met for any kind of drug.
Gene: Protein-coding gene on chromosome 21 (36,699,115 to 36,749,917, forward strand). Ensembl gene ENSG00000159263.
Subcellular location: Nucleus
Subcellular location (Human Protein Atlas): Nuclear bodies; Nucleoplasm
Gene Ontology:
Molecular function: protein binding; DNA binding; DNA-binding transcription factor activity; DNA-binding transcription factor activity, RNA polymerase II-specific; RNA polymerase II transcription regulatory region sequence-specific DNA binding; protein dimerization activity; protein heterodimerization activity
Biological process: nervous system development; regulation of transcription by RNA polymerase II; regulation of DNA-templated transcription; system development
Cellular component: nuclear body; nucleoplasm; chromatin; nucleus
Genetic constraint (gnomAD): Loss-of-function variants: 28 observed, 57.59 expected, observed/expected ratio (o/e) 0.49, 90% interval 0.36 to 0.67. The upper end of that interval is the gene's LOEUF score, 0.67, which puts it in group 2 of 6, group 1 being the genes least tolerant of losing a copy. Missense variants: 808 observed, 773.79 expected, observed/expected ratio (o/e) 1.04, 90% interval 0.99 to 1.11. Synonymous variants: 395 observed, 339.98 expected, observed/expected ratio (o/e) 1.16, 90% interval 1.07 to 1.26.
Homologues: Orthologues: chimpanzee SIM2 (99% identical), macaque SIM2 (97% identical), dog SIM2 (94% identical), pig SIM2 (93% identical), mouse Sim2 (90% identical), rat Sim2 (89% identical), guinea pig SIM2 (83% identical), rabbit SIM2 (80% identical), tropical clawed frog sim2 (71% identical), Drosophila melanogaster trh (26% identical), Drosophila melanogaster sima (23% identical), Caenorhabditis elegans hif-1 (18% identical). Paralogues in human: SIM1 (57% identical), NPAS3 (33% identical), HIF1A (27% identical), NPAS1 (26% identical), EPAS1 (24% identical), HIF3A (24% identical), NPAS4 (18% identical).
Diseases named in the same sentence as SIM2 in open-access papers:
SIM2 is named in the same sentence as 49 diseases in open-access papers, as found by Europe PMC text mining. Sharing a sentence is not in itself a finding about the gene and the disease. The quoted sentences say what the papers report.
prostate carcinoma (12 papers, 2011 to 2024). A carcinoma that arises from epithelial cells of the prostate gland. "Our study reported a combined role of both isoforms of the SIM2 implicated in the prostate cancer cell." (PMID 22174909, 2011). "Taken together, our results suggest an involvement of SIM2 in key traits of prostate tumor cell biology and might underlie a contribution of this transcription factor to prostate cancer onset and progression." (PMID 22174909, 2011). "SIM2 is identified overexpressed in prostate cancer tissues as well, and works as a potential target for the immunotherapy of prostate cancer." (PMID 36882451, 2023). "Other genes that are regulated by acK609-AR include single-minded homolog 2 (SIM2), which is known to be the highly up-regulated gene in prostate cancer, and its isoform SIM2-s, a marker for aggressive prostate cancer." (PMID 35704598, 2022). "Especially in prostate cancer, various studies have reported an increased expression of SIM2 and its contribution to tumor progression and aggressiveness." (PMID 29109451, 2017). "SIM2 mRNA expression was the highest in prostate cancer, and CvSCC was the fifth highest in all cancers." (PMID 29109451, 2017). "The expression of SIM2, a transcription factor, is increased in prostate cancer and its hypomethylation status (ratio 0.41) in stromal tissue provides evidence that SIM2 transcription is upregulated." (PMID 25799167, 2015). "Previously, we reported that SIM2 was an ideal target for prostate cancer immunotherapy, being a protein overexpressed in prostate cancer with little expression in peripheral tissue." (PMID 24690990, 2014). "We and others have previously demonstrated overexpression and specificity of SIM2 in prostate cancer patients." (PMID 24690990, 2014). "We have previously reported SIM2 as a potential biomarker and immunotherapy target for human prostate cancer." (PMID 22174909, 2011). "In the present study we attempted to characterize the role of SIM2 in prostate cancer using a short hairpin RNA-induced gene silencing approach in PC3 cells as a model." (PMID 22174909, 2011). "This study was designed to elucidate the role of SIM2 in prostate cancer using a shRNA-based approach in the PC3 prostate cancer cell line." (PMID 22174909, 2011). "Validation in plasma samples from prostate cancer patients and cancer-free individuals underscored the diagnostic and prognostic relevance of two genes, OR51E2 and SIM2, along with two miRNAs, miR-200c and miR-200b, in distinguishing prostate cancer presence with notable sensitivity and specificity." (PMID 38542382, 2024). "SIM2-s was dysregulated in glioma, prostate cancer, breast cancer, colorectal cancer, and ESCC." (PMID 27818681, 2016). "We therefore analysed the expression of SIM2 mRNA by quantitative real time PCR in stable LNCaP prostate cancer cell lines to determine whether there was any background expression that was undetectable by western blot." (PMID 25768837, 2015). "In addition, SIM2 is the second most consistently over expressed gene in prostate cancer and over expression of the short isoform of SIM2 (SIM2s) is reported in malignant colon, pancreas, and prostate tissues as compared to the corresponding normal tissues." (PMID 23343470, 2013). "We found that SIM2 genes are detectable in all these prostate cancer cells by real time PCR." (PMID 22174909, 2011). "However the expression levels in DU145 and LNCaP are relatively lower than other prostate cancer cells while PC3 cells express moderate level of SIM2 genes which are consistent with other report." (PMID 22174909, 2011). "We therefore examined the effects of downregulation of SIM2 in prostate cancer cells." (PMID 22174909, 2011). "Distinguishing the roles of SIM2s and SIM2L may have more profound meaning to understand the functional role of SIM2 in prostate cancer progression, which is our next step to uncover more significance of this gene." (PMID 22174909, 2011).
prostate carcinoma (continued). "However, the exact role of SIM2 in cancer in general, and in prostate cancer in particular, remains largely unknown." (PMID 22174909, 2011). "A prior in silico bioinformatics approach using the Cancer Genome Anatomy Project (CGAP) database of the National Cancer Institute (NCI) identified SIM2 as associated with colon, pancreas and prostate carcinomas, while absent in the corresponding normal tissues." (PMID 22174909, 2011). "Recent reports have suggested a possible involvement of Single-minded homolog 2 (SIM2) in human solid cancers, including prostate cancer." (PMID 22174909, 2011). "The silencing also reduced proliferation of CRPC cells and tumor size in chick embryo chorioallantoic membrane assay, further emphasizing the importance of SIM2 in CRPC cells and pointing to the functional relevance of this potential prostate cancer biomarker in CRPC cells." (PMID 34127815, 2021). "Based on our prior genome-wide interrogation of human prostate cancer tissues to identify genes over-expressed in cancer and absent in the periphery, we targeted SIM2 as a prototype autologous tumor antigen for these studies." (PMID 24690990, 2014). "Using a genome-wide interrogation strategy to identify genes that are expressed abundantly in human prostate cancer but sparsely in non-cancerous adult tissues, we previously identified numerous putative prostate TAAs including ETS related gene (ERG) and Single-minded homolog 2 (SIM2)." (PMID 24690990, 2014).
breast carcinoma (9 papers, 2013 to 2025). "SIM2 has further been proposed to have a breast tumor suppressive activity and a genome-wide linkage scan identified three putative breast cancer susceptibility loci, one of which (21q22) harbors SIM2." (PMID 23343470, 2013). "Here, we show that the breast tumor suppressor gene SIM2 promotes mitochondrial oxidative phosphorylation (OXPHOS) using breast cancer cell line models." (PMID 37121978, 2023). "To confirm that activation of NFκB downregulates SIM2 expression in breast cancer cells, we cloned a 2-kb portion of the SIM2 promoter upstream of the luciferase gene and co-transfected with increasing amounts of p65 in MCF7 cells." (PMID 31783895, 2019). "In particular, colon cancer had more than a 4-fold increase in SIM2 expression, and breast cancer had more than a 2-fold increase." (PMID 24690990, 2014). "Combined with previous studies, we hypothesize that the methylation of SIM2 is a potential key regulation mechanism in the procession of breast cancer." (PMID 36882451, 2023). "Many studies reported that SIM2 plays a significant role in breast cancer." (PMID 36882451, 2023). "Finally, the roles of BEND3 and SIM2 in tumor immune microenvironment in breast cancer was obtained using online web tools, which requires more experimental validations." (PMID 36882451, 2023). "Furthermore, immunostaining of lysates from breast cancer cells overexpressing SIM2s showed reduction in various NFκB signaling proteins, as well as pAkt, whereas knockdown of SIM2 revealed increases in NFκB signaling proteins and pAkt." (PMID 31783895, 2019). "In fact, SIM2 has been shown to suppress breast cancer growth and invasion in a xenograft model." (PMID 24690990, 2014). "SIM2 is similarly overexpressed in several other malignancies, including colon cancer, breast cancer, cervical cancer, pancreatic cancer and oligodendroglioma, suggesting SIM2 may be an attractive target for immunotherapy of a wide range of cancers." (PMID 24690990, 2014). "Our future studies will further uncover the mechanism(s) by which SIM2 regulates STING under normal developmental conditions as well as in cancer and assess the use of this relationship as a therapeutic benefit in breast cancer treatment options." (PMID 39399905, 2024). "To further determine the effect of SIM2s on metabolism, we generated CRISPR/Cas9 SIM2 knock-out (SIM2KO) cells, which also underwent an EMT and overexpressed FLAG-tag labeled SIM2s (SIM2s-FLAG) in SUM159 breast cancer cells that did not express SIM2s43,44,48." (PMID 37121978, 2023).
Down syndrome (9 papers, 2013 to 2025). "Although current evidence suggests an association between SIM2 and Down syndrome, its precise role in the pathogenesis of this condition requires further detailed investigation." (PMID 41458630, 2025). "The HSA21 encoded Single-minded 2 (SIM2) transcription factor has key neurological functions and is a good candidate to be involved in the cognitive impairment of Down syndrome." (PMID 25955728, 2015). "Human SIM2 was initially identified by positional cloning around the Down Syndrome (DS) critical region of chromosome 21 and is amplified in DS patients and mouse models." (PMID 37121978, 2023). "SIM2 is located within the critical region of Down syndrome in the human genome, suggesting that it may play a role in the complex etiology of this disorder." (PMID 41458630, 2025). "The location of SIM2 within the Down syndrome critical region (DSCR) on human chromosome 21 stimulated the proposal that SIM2 may be one of the genes contributing to the complex aetiology of this condition." (PMID 35730699, 2022). "Single-minded homolog 2 (SIM2), a member of the basic HLH (helix-loop-helix)-PER-ARNT-SIM (bHLH-PAS) transcription factors, is identified within a Down’s syndrome-crucial region of chromosome 2111–13." (PMID 29109451, 2017). "SIM2 is located within the Down syndrome critical region (DSCR) of chromosome 21, and manipulation in mouse models suggests Sim2 may play a role in brain development and function." (PMID 35730699, 2022). "And while the exact molecular details of SIM2 action during development and beyond are still not entirely clear, it is known that Down syndrome patients have numerous amino acid changes in the SIM2 protein that in vitro impair its function as a transcription factor." (PMID 40115535, 2025).
glioma (5 papers, 2016 to 2025). A benign or malignant brain and spinal cord tumor that arises from glial cells (astrocytes, oligodendrocytes, ependymal cells). "To deliver VIVIT to glioma cells, we used a Sim2 peptide, as the Sim2-conjugated VIVIT showed the inhibitory activity on NFAT signaling in other cells." (PMID 34443374, 2021). "Previous study showed that down-regulation of miR-200a promoted glioma malignancy by up-regulating SIM2-s." (PMID 27267902, 2016). "Additionally, HOXC10 and SIM2 demonstrated significant overexpression in human GBM (p ≤ 0.0001) and human ODG (p ≤ 0.04), respectively, but not in the other human glioma subtypes." (PMID 31475119, 2019).
colorectal cancer (3 papers, 2016 to 2023). A primary or metastatic malignant neoplasm that affects the colon or rectum. "As an oncogene, TMEM75 promotes colorectal cancer progression relying on the activation of SIM2, while its role in GC has not been identified." (PMID 37291405, 2023).
colon cancer (2 papers, 2011 to 2014). "Antisense inhibition of SIM2-s expression by antisense oligos caused growth inhibition and apoptosis in colon cancer cell line RKO and tumor growth in nude mice and also in pancreatic cancer cell line CAPAN-1." (PMID 22174909, 2011). "Suppression of SIM2 short isoform (SIM2s) by antisense oligonucleotides reduced tumor growth in colon cancer cells and induced CAPAN-1 pancreatic cell death through apoptosis." (PMID 22174909, 2011). "SIM2-s was specifically expressed in early stages of colon cancer." (PMID 22174909, 2011).
Intellectual disability (2 papers, 2017 to 2022). "Phenotypes in common between some patients harbouring functionally deficient SIM2 alleles include intellectual disabilities, delayed speech, seizure disorders, hypotonia, dysmorphic features and scoliosis." (PMID 35730699, 2022). "Recently a study proposed a homozygous SIM2 variant (p.Tyr154Cys) as the cause of the clinical presentation in a child with craniofacial abnormalities, developmental delay and intellectual disability." (PMID 35730699, 2022). "Exome sequencing data from patients with intellectual disabilities revealed many non-synonymous single-nucleotide variants in the SIM2 gene." (PMID 35730699, 2022). "Given the phenotypes of Sim2 KO mice, it is possible that mutations in SIM2 may be causing or contributing to human developmental disorders including intellectual disabilities, facial dysmorphologies and congenital scoliosis." (PMID 35730699, 2022).
pancreatic cancer (2 papers, 2014 to 2023). "For example, in pancreatic cancer, the silence of SIM2-s (the short form of SIM2) significantly induces CAPAN-1 cell death via apoptosis." (PMID 36882451, 2023).
benign prostate hyperplasia (1 paper, 2021). "Analysis of a PCa cohort concluded that the expression of SIM2 mRNA is significantly higher in PCa than in benign prostate hyperplasia, with CRPC showing a further increasing trend in the expression." (PMID 34127815, 2021).
bladder cancer (1 paper, 2023). "This test is based on the evaluation of three methylation biomarkers, TRNA-Cys, SIM2, and NKX1-1, and showed a sensitivity of 93.5% and a specificity of 92.6% in detecting bladder cancer." (PMID 37511475, 2023).
ductal carcinoma in situ (1 paper, 2023). "Moreover, SIM2 staining in human ductal carcinoma in situ (DCIS) lesions revealed that SIM2 expression was not exclusive to the nucleus." (PMID 37121978, 2023).
esophageal cancer (1 paper, 2022). A primary or metastatic malignant neoplasm involving the esophagus. "Additionally, the lincRNA CASC15 is thought to recruit the demethylase FTO to SIM2, decreasing SIM2 mRNA stability and promoting esophageal cancer progression." (PMID 35368653, 2022).
glioblastoma (1 paper, 2011). The most malignant astrocytic tumor (WHO grade IV). "The transcription factor c-myb regulates SIM2 transcription in glioblastoma cells, and a nuclear localization signal (NLS) mediates nuclear localization of SIM2." (PMID 22174909, 2011). "SIM2 regulates the expression of MMP-2 and TIMP-2, which drive its role in glioblastoma cells." (PMID 22174909, 2011).
head and neck cancer (1 paper, 2014). A primary or metastatic malignant neoplasm affecting the head and neck. "Interestingly, while an overexpression of SIM2 in cancer might suggest a tumorigenic role for SIM2, its frequent down-regulation in other cancers such as oesophageal, kidney, and head and neck cancers might suggest a tumor suppressive role." (PMID 24690990, 2014).
invasive ductal carcinoma (1 paper, 2024). "It has previously been shown that single-minded 2 (SIM2) functions as a tumor suppressor within the mammary gland, as we observed a loss of Sim2 expression with progression to invasive ductal carcinoma." (PMID 39399905, 2024).
Obesity (1 paper, 2026). Accumulation of substantial excess body fat. "One human SIM1 early onset obesity variant, SIM1.R171H, is within the PAS-A -AT-Hook region predicted to contact DNA and has been shown to possess only 30% of wildtype (WT) SIM1 activity, a trait that is shared with its paralog SIM2." (PMID 41495897, 2026).
prostate adenocarcinoma (1 paper, 2025). "The volcano plot indicated significant upregulation of genes such as SIM2, HPN, and HOXC6 in prostate adenocarcinoma (PRAD), and significant downregulation of genes such as SLC39A2, SLC39A6, and SLC39A10." (PMID 40978029, 2025).
prostate tumors (1 paper, 2011). "Thanks to its overexpression in prostate tumors and its highly restricted expression in humans, we proposed to use SIM2 as an immunotherapy target and were able to identify 5 HLA-A2.1, SIM2-derived immunogenic epitopes." (PMID 22174909, 2011).
scoliosis (1 paper, 2022). A congenital or acquired spinal deformity characterized by lateral curvature of the spine. "Many the patients with SIM2 variants (E19K, V326M, R163X) have scoliosis, a phenotype that is seen in both the heterozygous and homozygous Sim2 knockout mouse model with incomplete penetrance." (PMID 35730699, 2022). "Together these observations suggest that SIM2 may be a susceptibility allele for scoliosis, increasing the incidence of this phenotype, likely in combination with environmental stresses (such as hypoxia) or other gene variants." (PMID 35730699, 2022).
triple-negative breast carcinoma (1 paper, 2024). An invasive breast carcinoma which is negative for expression of estrogen receptor (ER), progesterone receptor (PR), and human epidermal growth factor receptor 2 (HER2). "To further investigate the relationship between SIM2 and STING, we employed use of a model of triple negative breast cancer (TNBC)." (PMID 39399905, 2024).